HAMP (hepcidin antimicrobial peptide)
Diseases named in the same sentence as HAMP in open-access papers (continued):
Sharing a sentence is not in itself a finding about the gene and the disease.
bacterial infection (8 papers, 2012 to 2026). "The majority of these results suggest that both HFE and Hepcidin (encoded by the HFE and HAMP genes, respectively) play a protective role against bacterial infection in human and mouse." (PMID 28815056, 2017). "Hepcidin (gene name hepcidin antimicrobial peptide (HAMP)), a key negative regulator of iron metabolism in the body, was originally identified as having antimicrobial properties against bacterial infections." (PMID 22570668, 2012). "Hepcidin antimicrobial peptide (HAMP), also named LEAP-1 (Liver-expressed antimicrobial peptide 1) is one kind of cysteine-rich AMPs and is a key molecule of the innate immune system against bacterial infections and in iron metabolism in organisms." (PMID 22511989, 2012). "Hepcidin antimicrobial peptide (HAMP) is a small cysteine-rich peptide and a key molecule of the innate immune system against bacterial infections." (PMID 22511989, 2012).
HAMP also shares sentences with these, for which no sentence is quoted: chronic kidney disease (4 papers); colorectal cancer (4); kidney disease (3); Hyperferritinemia (2); inflammatory bowel disease (2); non-small cell lung carcinoma (2); renal cell carcinoma (2); acute kidney injury (1); adenocarcinoma (1); autoimmune disease (1); autoimmune thyroid disease (1); bacteremia (1); breast hyperplasia (1); cardiovascular disease (1); cholestasis (1); colon adenocarcinoma (1); diabetes (1); End Stage Renal Disease (1); endotoxemia (1); esophageal carcinoma (1); fibrosis (1); genetic disorders of (1); glioblastoma multiforme (1); head and neck squamous cell carcinoma (1); heart attack (1); heart failure (1); hemochromatosis type 2A (1); hemochromatosis type 2B (1); Huntington disease (1); hyperprolactinemia (1).
A further 24 diseases each share a sentence with HAMP in 1 paper.